AHR (aryl hydrocarbon receptor)
Diseases named in the same sentence as AHR in open-access papers (continued):
Sharing a sentence is not in itself a finding about the gene and the disease.
brain tumors (14 papers, 2013 to 2022). "The TDO2–kynurenine–AhR pathway is active in human brain tumors and is associated with malignant progression and poor survival." (PMID 32325928, 2020). "In addition, kynurenine acts as an endogenous ligand of the human AhR, and the TDO-AhR pathway is associated with the malignant progression of human brain tumors." (PMID 24330582, 2013). "In fact, while AHR is able to repress TGF-β signaling in brain tumors, TGF-β is also needed for the maintenance of proper AHR expression levels in lymphocytes." (PMID 36499247, 2022). "A comprehensive study in human brain tumors revealed that TDO2‐derived Kyn activates AhR in an autocrine/paracrine manner to promote tumor growth." (PMID 34101386, 2021). "The role of AhR in brain tumors is complicated, depending on the type of tumor, on ligands that activate AhR, and other features of the pathological process." (PMID 32325928, 2020). "Medulloblastoma, a primary brain tumor in children, derives from abnormally proliferating precursors of cerebellar neurons in which AhR is overexpressed." (PMID 32325928, 2020). "In this review, we summarize current knowledge about AhR in relation to brain tumors and provide an overview of AhR’s potential as a therapeutic target." (PMID 32325928, 2020). "Lately, there is growing evidence that aryl hydrocarbon receptor (AhR) plays an important part in the development of brain tumors." (PMID 32325928, 2020). "Others and we have demonstrated that kynurenine activates the AHR signaling pathway in mouse immune cells and human brain tumor cells." (PMID 24657910, 2014). "A recent study demonstrated that the tryptophan catabolism enzyme TDO is overexpressed in human brain tumors, and elevated secretion of kynurenine promotes cell migration via an AhR-dependent pathway." (PMID 25060643, 2014). "Kynurenine activated AhR pathway in brain tumors, cancer progression, and inflammation." (PMID 36499198, 2022). "Given the important roles of AhR in immunomodulation, tumor evasion and cell cycle biology, future studies focusing on inflammation mediated Kyn-AhR signaling demand attention as a potential therapeutic target for brain tumors and neuroinflammation." (PMID 34205235, 2021). "Emerging evidence has demonstrated the role of the AhR and its ligands in brain tumors." (PMID 29487603, 2018). "Taken together, these data suggest that the AhR may affect the growth of brain tumors and antitumor immune responses." (PMID 29487603, 2018). "There is evidence that the TDO2–kynurenine–AhR signaling pathway is not specific for brain tumors but rather is a common feature of cancerous tumors." (PMID 32325928, 2020).
lung fibrosis (14 papers, 2016 to 2025). "Modules 1 to 5 are most closely linked to the lung fibrosis pathway, IL-3 signaling pathway, oxidative stress pathway, Aryl hydrocarbon receptor pathway, and Nrf2 pathway, respectively." (PMID 33066647, 2020). "Deficiency of γδTCR or inhibition of AhR signaling aggravated lung fibrosis, which was restored by nasal inhalation of recombinant IL-22." (PMID 32708044, 2020). "Preventing expression of IL-22 by mutating the aryl hydrocarbon receptor (AhR)—or inhibiting AhR signaling—accelerated lung fibrosis." (PMID 27824548, 2016). "When we administered blm to AHRΔex2 mice, we noted increased fibrosis in comparison to control mice that was still AHR dependent, indicating that loss of canonical AHR signaling in CD11c+ cells resulted in increased ncAHR signaling that exacerbated pulmonary fibrosis." (PMID 39964756, 2025). "DCs have been primarily appreciated for their role in bridging adaptive and innate immunity, including through increasing Th17 differentiation in pulmonary fibrosis, a process itself mediated by AHR." (PMID 39964756, 2025). "Using the bleomycin (blm) mouse model of pulmonary fibrosis, we demonstrate that AHR+ DCs accumulate in the lungs and drive production of IL-6 in an AHR-dependent fashion." (PMID 39964756, 2025). "The role of tryptophan metabolism and AHR signaling in mediating pulmonary fibrosis is also currently unclear." (PMID 39964756, 2025). "Tryptophan derivatives induce hyperimmune response through AhR signaling and participate in autophagy to alleviate pulmonary fibrosis." (PMID 38362497, 2024). "It is well known that regulatory T cells (Tregs) are critical for inflammation suppression, and AhR activation by FICZ attenuates IPF by increasing Tregs but inhibiting inflammatory T cell subsets in a bleomycin-induced lung fibrosis model." (PMID 35656117, 2022). "We confirmed that pro-inflammatory cytokines released by the macrophage cell initiate the EMT process and macrophages were important for the progression of pulmonary fibrosis relying on AhR agonists." (PMID 36355934, 2022). "Since the migration of epithelial cells is the first step in the process of pulmonary fibrosis, we treated both macrophage and epithelial cells with AhR agonists." (PMID 36355934, 2022). "Collectively, our study explored EMT progression induced by pro-inflammatory cytokines released by macrophages upon AhR activation and the role of Wnt/β-catenin in pulmonary fibrosis pathogenesis." (PMID 36355934, 2022). "AhR can promote the β-catenin-mediated epithelial-mesenchymal transition, which promotes the initiation and progression of lung fibrosis, by regulating relevant biochemical mechanisms such as phosphorylation via downstream components." (PMID 36355934, 2022). "The present study pursued how AhR agonist treatment affected the expression of molecules involved in ECM metabolism during lung fibrosis." (PMID 36355934, 2022). "The ability of FICZ to attenuate pulmonary fibrosis by modulating the immune system via AhR has also been reported." (PMID 35628213, 2022). "Here, we present evidence that AHR plays a role in controlling IL-17 responses and the development of pulmonary fibrosis in response to respiratory pathogens following bone marrow transplant (BMT)." (PMID 33491663, 2021). "We demonstrated that stimulation of AhR signals by FICZ attenuated lung fibrosis and improved the survival rate of mice with pulmonary fibrosis induced by BLM." (PMID 32033616, 2020). "Bleomycin-challenged mice with treatment of FICZ, a natural AhR ligand, exhibited increased number of Tregs with attenuated lung fibrosis, suggesting a therapeutic potential of targeting AhR for treating fibrotic diseases." (PMID 32708044, 2020). "Our findings suggest that stimulation of AhR signals attenuated lung fibrosis by increasing Tregs and suppressing inflammatory T cell subsets in a BLM-induced fibrosis model." (PMID 32033616, 2020).
lung fibrosis (continued). "Interestingly, another group using a similar AHR exon 2 deletion mutant saw a similar aggravated pulmonary fibrosis phenotype when using a blm model." (PMID 39964756, 2025). "Inhibition of AHR signaling ameliorated development of blm-induced pulmonary fibrosis." (PMID 39964756, 2025). "Kynurenine is increased with aging, and kynurenine elevation could signal through AhR to accelerate lung fibrosis by promoting epithelial-to-mesenchymal transition." (PMID 35656117, 2022). "Notably, the IDO1/AHR axis was recently shown to drive, at least in part, severe lung inflammation and pulmonary fibrosis following allogeneic stem cell transplant." (PMID 33491663, 2021). "Taken together, we hypothesize that FICZ attenuated lung fibrosis induced by BLM via AhR and at least one of the mechanisms was expanding CD4+ Tregs." (PMID 32033616, 2020). "Taken together, our results indicate that the immunological changes induced by AhR stimulation may contribute to attenuating lung fibrosis induced by BLM." (PMID 32033616, 2020). "We previously published that AHR+ CD103+ DCs were recruited to lungs, and drove lung injury and fibrosis following bone marrow transplantation and herpesvirus infection; however, a pathogenic role for AHR and DCs in noninfectious forms of pulmonary fibrosis is not known." (PMID 39964756, 2025). "Thus, we hypothesized that AhR signaling may also be involved in the process of lung fibrosis via its modulatory effects on the immune system." (PMID 32033616, 2020). "We have previously defined an important role for tissue-resident DCs, and more specifically DCs expressing the aryl-hydrocarbon receptor (AHR), in virus-mediated pulmonary fibrosis following bone marrow transplantation." (PMID 39964756, 2025). "Another study, illustrating the antifibrotic potential of aryl hydrocarbon receptor, found that stimulation of aryl hydrocarbon receptor alleviated the BLM-induced pulmonary fibrosis in mice, which was concomitant with an increase in CD4+FoxP3+ Treg." (PMID 39737178, 2024). "Our study suggests that the effects of an AhR ligand, FICZ, on AhR led to increase the number of Tregs and reduced that of CD4+IFNγ+ T cells and contributed to alleviating lung fibrosis." (PMID 32033616, 2020). "We investigated the effects of AhR signals on the process of lung fibrosis and changes in immunological features using a bleomycin (BLM)-induced lung fibrosis mouse model." (PMID 32033616, 2020). "TGF-β/Smad signaling is widely recognized as the core pathway of fibrosis, and AhR may attenuate lung fibrosis by inducing Smad4 degradation in the proteasome under non-ligand conditions." (PMID 35656117, 2022). "To elucidate whether AhR signals affect the process of lung fibrosis induced by BLM, we used FICZ as an AhR ligand due to its lack of toxicity and high affinity for AhR." (PMID 32033616, 2020).
Non-Alcoholic Fatty Liver Disease (14 papers, 2021 to 2026). "Emerging evidence suggests that the AHR is a novel regulator of nonalcoholic fatty liver disease, and its activation can induce lipid oxidation and lipogenic pathways." (PMID 35897801, 2022). "Here, we aimed to identify a novel mechanism linking intestinal Akkermansia muciniphila and the aryl hydrocarbon receptor (AHR) to saccharin/sucralose-induced nonalcoholic fatty liver disease (NAFLD) in mice." (PMID 33622853, 2021). "Notably, AHR activation by microbial tryptophan metabolites were shown to improve alcohol-related liver disease and non-alcoholic fatty liver disease." (PMID 37422682, 2023). "Recently, a significant number of studies investigating the role of AhR in metabolic diseases, including non-alcoholic fatty liver disease (NAFLD) have been conducted." (PMID 37284280, 2023). "Roles of AHR and NAD-consuming enzymes have been discussed using infectious inflammation (bacterial infection) and sterile inflammation (nonalcoholic fatty liver disease) as examples." (PMID 34559251, 2021). "In the last couple of years, several studies addressing AHR function in nonalcoholic steatohepatitis (NASH) and nonalcoholic fatty liver disease (NAFLD) have emerged." (PMID 34075438, 2021).
vitiligo (14 papers, 2014 to 2025). Generalized well circumscribed patches of leukoderma that are generally distributed over symmetric body locations and is due to autoimmune destruction of melanocytes. "Further, this group found that the expression of AhR and its downstream target genes encoding cytochrome P450 1A1 and cyclooxygenase 2 is decreased in the skin lesions of vitiligo patients." (PMID 35320978, 2022). "The other way round, dysregulation of epidermal AHR signaling, is associated with vitiligo, a depigmentation disorder of the skin associated with progressive loss of melanocytes." (PMID 31795255, 2019). "We previously identified the T allele of AHR −129C > T variant as a protective factor against vitiligo." (PMID 26370050, 2015). "To further understand another significance of AHR −129C > T polymorphism, we assessed the impact of this functional variant on the immune cytokines in vitiligo." (PMID 26370050, 2015). "In consideration of the critical role of AHR in both melanocyte and cellular immunity and aberrant AHR pathway in vitiligo, we previously evaluated the potential association between AHR polymorphisms and vitiligo susceptibility." (PMID 26370050, 2015). "In the current study, we investigated the molecular mechanisms of AHR functional variation (−129C > T polymorphism) underlying its association with vitiligo." (PMID 26370050, 2015). "We further detected AHR related cytokines in vitiligo patients and observed declined serum IL-10 level and its association with the AHR −129C > T variant." (PMID 26370050, 2015). "Reduced expression of the AHR has been associated with the progression of unstable vitiligo." (PMID 40703229, 2025). "In addition, the relation between AhR gene functional mutations and vitiligo susceptibility has been suggested." (PMID 38361944, 2024). "AHR polymorphisms might play a role in Treg cell differentiation, IL-10, IL-17, and IL-22 expression, thus contributing to vitiligo pathogenesis." (PMID 36551332, 2022). "AhR-mediated Treg cell differentiation and IL-10 expression may be associated with vitiligo pathogenesis, as IL-10 plays a crucial role in the development of self-tolerance." (PMID 33499346, 2021). "IL-22-producing cells, whose activity is dependent on AhR ligation, may also contribute to abnormal immune response underlying vitiligo." (PMID 33499346, 2021). "Accordingly, it could be speculate that the AHR −129C > T polymorphism might be associated with vitiligo through influencing AHR expression and its downstream melanogenic factors." (PMID 26370050, 2015). "The association between AHR expression and vitiligo remains to be elucidated." (PMID 26370050, 2015). "Interestingly, increased AHR expression was observed in carriers of the −129 T allele; thus, it could potentially be a genetic marker for vitiligo." (PMID 33499346, 2021). "Consequently, our data of genetic analysis imply that the AHR −129C > T mutation might be related to vitiligo partially by affecting IL-10 production, which further supports previous findings about AHR function in immune regulation." (PMID 26370050, 2015). "In fact, narrow-band UVB, the most widely used therapy for vitiligo, probably induces repigmentation by activating AhR signaling." (PMID 38361944, 2024). "Activation of AhR signaling conduces to progression control and repigmentation, showing great potential in vitiligo treatment." (PMID 38361944, 2024). "Current opinions reveal that AhR signaling pathway is essential for vitiligo treatment through antioxidant, immune modulation, and melanogenesis effects." (PMID 38361944, 2024). "Here, we review the relevant literature and summarize the possible roles of the AhR signaling pathway in vitiligo pathogenesis and treatment, to further understand the links between the AhR and vitiligo, and provide new potential therapeutic strategies." (PMID 38361944, 2024).
vitiligo (continued). "Here, we review the relevant literature, summarize the possible roles of AhR pathway in vitiligo pathogenesis, and conclude the current AhR agonists and antagonists studied in vitiligo, to advance our knowledge and provide new insight into potential therapy." (PMID 38361944, 2024). "Even in vitiligo, L-tryptophan metabolism influences the immune response, ROS, and aryl hydrocarbon receptor-mediated immune response signaling." (PMID 35625824, 2022). "In vitiligo, melanocytes show poor antioxidant capacity due to alterations in antioxidant mechanisms, such as AHR and NRF2/ heme oxygenase-1(HO-1) system, which result in high levels of superoxide dismutase and low levels of catalase." (PMID 36551332, 2022). "The expression of AhR in peripheral blood mononuclear cells of vitiligo patients is decreased and is closely related to disease severity." (PMID 35320978, 2022). "AhR agonists are the active ingredients in some traditional herb formulations for vitiligo; to illustrate, tapinarof, isopsoralen, and norisoboldine are potentially new targets for its treatment." (PMID 35320978, 2022). "Therefore, AHR − 129C > T polymorphism may be related to vitiligo by altering IL-10 production." (PMID 33499346, 2021). "AhR−/− mice showed lower tyrosinase activity, and mutations of the AHR gene were also associated with vitiligo susceptibility." (PMID 33381211, 2020). "Consistently, lower transcription level of AhR was observed in the skin lesions of vitiligo patients." (PMID 33381211, 2020). "We also found decreased AHR transcript expression in the PBMCs of vitiligo patients, which was negatively correlated with disease duration." (PMID 26370050, 2015). "The aryl hydrocarbon receptor (AHR) is essential for melanocyte homeostasis and immune process, and abnormal AHR was observed in vitiligo." (PMID 26370050, 2015). "AhR signaling plays important roles in modulating T cell differentiation and function, which is likely to be an appealing target to combat abnormal autoimmune in vitiligo." (PMID 38361944, 2024). "Recent studies suggested that AhR signaling pathway was downregulated in vitiligo." (PMID 38361944, 2024). "AhR activation enhanced IL-22 release in CD4+ T cells of vitiligo patients." (PMID 38361944, 2024). "Recent studies identified abnormal AhR expression in vitiligo." (PMID 38361944, 2024). "Recently, AhR has been reported to modulate pigment synthesis via interacting with melanogenic signaling, and dysregulated AhR pathway might be involved in the development of vitiligo." (PMID 33381211, 2020). "Additionally, significantly declined expressions of AHR and its target genes were observed in the epidermis of vitiligo patients." (PMID 26370050, 2015). "Gene expression analysis of PBMCs from independent cases and controls showed apparently decreased AHR mRNA level in vitiligo, which was clearly negatively correlated with disease duration of vitiligo patients, suggesting that down-regulation of AHR transcription is relative to vitiligo." (PMID 26370050, 2015). "In summary, we provide evidence that AHR –129C > T variant could lead to allele-specific binding of SP1 to AHR promoter and further modify its transcription and downstream effectors in vitiligo." (PMID 26370050, 2015). "Our review shows that AhR may be a potential target for vitiligo treatment." (PMID 38361944, 2024). "In addition to activating the PI3K/Akt pathway, cinnamaldehyde might inhibit abnormal activation of the AhR signaling pathway, reduce the production of ROS in keratinocytes, and could have a therapeutic effect on vitiligo." (PMID 35320978, 2022). "Thus, functional studies may be needed to explore the regulatory mechanisms of AHR pathway in the immune pathology of vitiligo further." (PMID 26370050, 2015). "AhR can protect melanocytes from oxidate stress damage by activating the Nrf2-ARE pathway, which is already recognized as an attractive target for vitiligo treatment." (PMID 38361944, 2024).